ARMC5 (armadillo repeat containing 5)
Description:
Substrate-recognition component of a BCR (BTB-CUL3-RBX1) E3 ubiquitin ligase complex that terminates RNA polymerase II (Pol II) transcription in the promoter-proximal region of genes. The BCR(ARMC5) complex provides a quality checkpoint during transcription elongation by driving premature transcription termination of transcripts that are unfavorably configured for transcriptional elongation: the BCR(ARMC5) complex acts by mediating ubiquitination of Pol II subunit POLR2A phosphorylated at 'Ser-5' of the C-terminal domain (CTD), leading to POLR2A degradation. The BCR(ARMC5) complex acts in parallel of the integrator complex and is specific for RNA Pol II originating from the promoter-proximal zone: it does not ubiquitinate elongation-stalled RNA Pol II. The BCR(ARMC5) complex also acts as a regulator of fatty acid desaturation by mediating ubiquitination and degradation of SCAP-free SREBF1 and SREBF2. Involved in fetal development, T-cell function and adrenal gland growth homeostasis. Plays a role in steroidogenesis, modulates steroidogenic enzymes expression and cortisol production.
Synonyms: FLJ13063; AIMAH2
Tractability: PROTAC: UniProt records ubiquitination sites on it; ubiquitination databases record sites on it.
Gene: Protein-coding gene on chromosome 16 (31,458,080 to 31,467,172, forward strand). Ensembl gene ENSG00000140691.
Subcellular location: Nucleus; Chromosome; Cytoplasm
Subcellular location (Human Protein Atlas): Cytosol; Nucleoplasm; Focal adhesion sites
Gene Ontology:
Molecular function: protein binding; ubiquitin-like ligase-substrate adaptor activity; ubiquitin protein ligase activity
Biological process: proteasome-mediated ubiquitin-dependent protein catabolic process; RNA polymerase II transcription initiation surveillance; anatomical structure morphogenesis; protein ubiquitination
Cellular component: chromatin; chromosome; Cul3-RING ubiquitin ligase complex; cytoplasm; nucleus; membrane
Genetic constraint (gnomAD): Loss-of-function variants: 29 observed, 51.24 expected, observed/expected ratio (o/e) 0.57, 90% interval 0.42 to 0.77. The synonymous counts are far from expectation, so gnomAD's model fits this gene poorly and the ratio says little. Missense variants: 1,189 observed, 1,202.5 expected, observed/expected ratio (o/e) 0.99, 90% interval 0.94 to 1.04. Synonymous variants: 680 observed, 570.06 expected, observed/expected ratio (o/e) 1.19, 90% interval 1.12 to 1.27.
Homologues: Orthologues: chimpanzee ARMC5 (99% identical), macaque ARMC5 (97% identical), dog ARMC5 (90% identical), pig ARMC5 (87% identical), mouse Armc5 (86% identical), rat Armc5 (85% identical), guinea pig ARMC5 (85% identical), tropical clawed frog armc5 (39% identical), zebrafish armc5 (35% identical), Drosophila melanogaster Rnb (19% identical), Caenorhabditis elegans T28F4.4 (17% identical).
Diseases named in the same sentence as ARMC5 in open-access papers:
ARMC5 is named in the same sentence as 57 diseases in open-access papers, as found by Europe PMC text mining. Sharing a sentence is not in itself a finding about the gene and the disease. The quoted sentences say what the papers report.
adrenal hyperplasia (14 papers, 2015 to 2025). "Armadillo repeat-containing 5 (ARMC5) gene is primarily associated with primary bilateral macronodular adrenal hyperplasia and Cushing's syndrome." (PMID 40130155, 2025). "Inactivating mutations in the tumor suppressor gene ARMC5 are a leading cause of primary bilateral macronodular adrenal hyperplasia and subsequent CS." (PMID 41305762, 2025). "In one family carrying the p.A110fs*9 ARMC5 defect, adrenal hyperplasia was associated with meningioma." (PMID 35625779, 2022). "ARMC5 mutation leads to more severe disease with higher hypercortisolism, larger adrenal hyperplasia, and a higher number of nodules." (PMID 34680514, 2021). "ARMC5 defects have also been linked to the development of meningiomas, as shown in one family with meningioma and adrenal hyperplasia with ARMC5 loss of heterozygosity in the meningioma DNA." (PMID 33776926, 2021). "Early recognition of atypical symptoms and screening for ARMC5 mutation in patients with primary bilateral macronodular adrenal hyperplasia has important clinical implications for the diagnosis and genetic counseling." (PMID 29343284, 2018). "Recent studies have shown that primary bilateral macronodular adrenal hyperplasia is caused by combined germline and somatic mutations of the ARMC5 gene." (PMID 29343284, 2018). "Patients with ARMC5 mutations may be at risk of developing primary bilateral macronodular adrenal hyperplasia, necessitating careful monitoring for signs of adrenal hyperplasia and hypercortisolism." (PMID 40130155, 2025). "In addition, germline variants in ARMC5 have been identified as a cause of primary bilateral macronodular adrenal hyperplasia." (PMID 35625779, 2022). "Additionally, germline pathogenic variants in ARMC5, a putative tumor suppressor, were found to be a cause of cortisol-producing primary bilateral macronodular adrenal hyperplasia." (PMID 33776926, 2021). "Thus, ARMC5 inactivation leads to resistance to apoptosis in adrenocortical cells, which causes adrenal hyperplasia leading to increased cortisol level." (PMID 29343284, 2018). "Among these are somatic mutations of PKA catalytic subunit alpha gene (PRKACA) in ACA, germline, and somatic mutations of armadillo repeat containing 5 gene (ARMC5) in primary bilateral macronodular adrenal hyperplasia and somatic alterations of the E3 ubiquitin ligase gene ZNRF3 in ACC." (PMID 26106367, 2015). "Additionally, primary bilateral macronodular adrenal hyperplasia and ARMC5 mutation both associated with somatic mutation, along with therapeutic agents like metyrapone, osilodrostat, and 11 beta-hydroxylase inhibitors, are likely to remain highly relevant research targets." (PMID 41305762, 2025). "Therefore, patients with PPNAD with ARMC5 gene mutation might combine with macronodular adrenal hyperplasia." (PMID 39006359, 2024). "ARMC5 germline mutations are responsible for up to 50% (near to 80% in Japanese) of familial or sporadic PMAH and lead to larger adrenal hyperplasia, higher hypercortisolism, a higher number of nodules, hypertension, higher fasting glucose, and HbA1c." (PMID 36553033, 2022). "This review discusses the last decades’ findings on genetic and molecular causes of bilateral adrenal hyperplasia, including the several mechanisms altering the PKA pathway, the recent discovery of ARMC5, and the role of the adrenal paracrine regulation." (PMID 34680514, 2021). "However, in 2013, the discovery of alteration of ARMC5 (armadillo repeat containing 5) in PBMAH brought new insights into the pathogenesis of bilateral adrenal hyperplasia." (PMID 34680514, 2021). "In all patients presenting bilateral adrenal hyperplasia, genetic screening should be offered, including at least the analysis of PRK1R1A in patients with PPNAD and the analysis of ARMC5 in patients with PBMAH." (PMID 34680514, 2021).
adrenal hyperplasia (continued). "Functional studies showed that the inactivation of ARMC5 leads to the inhibition of apoptosis and decreases the expression of MC2R and steroidogenic enzymes which may be involved in adrenal hyperplasia." (PMID 36553033, 2022).
Macronodular adrenal hyperplasia (13 papers, 2014 to 2026). "We report a case of primary bilateral macronodular adrenal hyperplasia (PBMAH) in a 63-year-old man with a novel germline armadillo repeat-containing protein 5 (ARMC5) variant of uncertain significance (c.2525T > C; p.Phe842Ser)." (PMID 41503047, 2026). "On the other hand, massive enlargement of adrenal glands was seen in the CT scans of individuals with primary bilateral macronodular adrenal hyperplasia (PBMAH) when deletion mutation occurred in amino acids 702–706 of ARMC5." (PMID 36553033, 2022). "Inactivating mutations of ARMC5 are responsible for the development of bilateral macronodular adrenal hyperplasia (BMAH)." (PMID 35862218, 2022). "Germline mutations in ARMC5 (Armadillo repeat-containing protein 5) have been identified in familial cases and are present in approximately 50% of sporadic cases of macronodular adrenal hyperplasia." (PMID 29439489, 2018). "Germline and somatic inactivating mutations in the putative tumor-suppressor gene ARMC5 (armadillo repeat containing 5)- a member of the armadillo/β-catenin-like repeat superfamily- can cause primary bilateral macronodular adrenal hyperplasia (a rare form of primary adrenal Cushing syndrome)." (PMID 36004349, 2022). "Before this study, loss-of-function heterozygous mutations affecting ARMC5 were detected in primary bilateral macronodular adrenal hyperplasia and ARMC5 was found to regulate the abundance of bulk Pol II via direct interaction." (PMID 39854452, 2025). "We demonstrated extensive genetic diversity of ARMC5 in a patient with primary bilateral macronodular adrenal hyperplasia that started with exophthalmos, which contributes to further understanding of the pathogenesis of this disease." (PMID 29343284, 2018).
Cushing syndrome (12 papers, 2015 to 2026). Cushing's syndrome (CS) encompasses a group of hormonal disorders caused by prolonged and high exposure levels to glucocorticoids that can be of either endogenous (adrenal cortex production) or exogenous (iatrogenic) origin. "The ARMC5 gene has been primarily linked to primary bilateral macronodular adrenal hyperplasia and Cushing's syndrome, with some studies reporting associations with primary aldosteronism." (PMID 40130155, 2025). "In contrast, patients with overt Cushing's syndrome and bilateral adrenal nodules had the presence of ARMC5 mutations that were with high prevalence and similar to the literature." (PMID 32117062, 2020). "In contrast, the frequency of patients with overt Cushing's syndrome and bilateral adrenal nodules due to the presence of ARMC5 mutations was similar to that found in the literature." (PMID 32117062, 2020). "When a clinician encounters a patient with a pathogenic and damaging ARMC5 variant, screening for Cushing syndrome and primary aldosteronism is encouraged." (PMID 30832344, 2019). "The ARMC5 gene has been recently implicated in endogenous hypercortisolemia due to a rare form of adrenocortical hyperplasia, termed primary bilateral macronodular adrenal hyperplasia (PBMAH)." (PMID 30832344, 2019). "We identified an ARMC5 pathogenic germline mutation in a patient (P-15) who presented with both Cushing’s syndrome and PA." (PMID 29370219, 2018). "In contrast, pathogenic germline allelic variants of ARMC5 were identified in 65% of patients with ACTH pituitary-independent Cushing's syndrome with bilateral adrenal nodules, and 6 new families were diagnosed, improving their clinical care to avoid future health adversities." (PMID 32117062, 2020). "Interestingly, among the five sporadic PBMAH patients with ARMC5 germline mutations, P-15 was diagnosed with not only Cushing’s syndrome but also PA, while the other four patients had only Cushing’s syndrome." (PMID 29370219, 2018). "Therefore, ARMC5-mutated patients are more frequently treated than wild-type patients, whether by adrenalectomy or by steroidogenesis inhibitors in order to control Cushing’s syndrome." (PMID 39910635, 2025). "In regard to the high frequency (20%) of mutations in ARMC5 gene in all index cases analyzed, its systematic genetic screening appears to be important for patients with PBMAH or Cushing syndrome." (PMID 26106367, 2015). "Firstly, although ARMC5 variants require a 'second hit' for tumorigenesis, such as in cases of Cushing's syndrome, the heterozygous variants in our patient did not lead to such manifestations." (PMID 40130155, 2025). "Compared to those harboring wild-type ARMC5, PBMAH patients with ARMC5 variants may have more advanced Cushing's syndrome." (PMID 35996143, 2022). "ARMC5 (OMIM: 615649; 16p11.2), a tumor suppressor gene, is responsible for a familial form of bilateral macronodular adrenocortical hyperplasia (PBMAH), a rare cause of Cushing syndrome." (PMID 36553564, 2022). "The same study also demonstrated that ARMC5-wild-type tumors are more frequently associated with subclinical Cushing syndrome and non-functioning status." (PMID 29594118, 2018). "It is notable that F1-II-4 had Cushing’s syndrome and a unilateral adrenal mass but no ARMC5 pathogenic germline mutation." (PMID 29370219, 2018). "To investigate Armadillo repeat-containing 5 (ARMC5) mutations in Chinese patients with familial and sporadic primary bilateral macronodular adrenal hyperplasia (PBMAH), we performed clinical data collection and ARMC5 sequencing for three PBMAH families and 23 sporadic PBMAH patients." (PMID 29370219, 2018). "Accordingly, 56% of patients with truncating ARMC5 variants are primarily referred to clinical departments in front of overt signs of Cushing’s syndrome, versus only 21% of patients with non-truncating pathogenic variants, for which the incidental diagnosis in abdominal imaging is far more frequent." (PMID 39910635, 2025).
Cushing syndrome (continued). "Therefore, we recommend the genetic analysis of ARMC5 for patients with established Cushing's syndrome and bilateral adrenal nodules rather than patients with unilateral AI." (PMID 32117062, 2020). "Therefore, we recommend the genetic analysis of ARMC5 for patients with established Cushing's syndrome and bilateral adrenal nodules rather than for patients with unilateral adrenal incidentaloma." (PMID 32117062, 2020). "ARMC5-related endocrine hypertension diseases typically develop in adulthood as either subclinical Cushing syndrome, with or without primary aldosteronism, or overt Cushing syndrome." (PMID 30832344, 2019).
meningioma (11 papers, 2015 to 2025). A generally slow growing tumor attached to the dura mater. "In patients with PBMAH, pathogenic variants in the ARMC5 gene are associated with the development of meningiomas." (PMID 40895499, 2025). "ARMC5 germline and somatic alterations have been associated with the occurrence of meningiomas in several patients, including familial cases." (PMID 39910635, 2025). "The observation in the meningeal tumor of a LOH of the locus or a mutation on the second allele supports that ARMC5 mutations are responsible for meningioma." (PMID 34680514, 2021). "ARMC5 variants have also been related to the occurrence of meningioma in some reports." (PMID 39910635, 2025). "But the real incidence of meningiomas in ARMC5 mutated patients remains unknown and needs to be extensively investigated, since no systematic brain imaging in these patients have been reported to date." (PMID 39910635, 2025). "Interestingly, a somatic mutation in ARMC5 gene has also been found in a meningioma in patients with an ARMC5 germline mutation and a PBMAH." (PMID 26106367, 2015). "Moreover, the epidemiological findings there is a relation with meningioma and ARMC5 mutation." (PMID 33544460, 2021). "In the current literature, besides these two cases with demonstrated somatic ARMC5 alterations, meningiomas have been reported in 10 other ARMC5 patients and in two Korean sisters reported before the identification of ARMC5." (PMID 39910635, 2025). "Meningiomas, which can be associated with PBMAH, are similarly suggested to develop through a second hit mechanism in the ARMC5 gene." (PMID 40895499, 2025). "The current researches show ARMC5 gene mutations, including meaningless and frameshifted mutation, have been deemed to the main cause of PMAH and a relation with meningioma." (PMID 33544460, 2021). "The ubiquitin‐proteasome system is an essential regulator of ARMC5, which serves as a new tumour suppressor protein for inhibiting meningiomas and hereditary adrenocortical tumorigenesis." (PMID 33544460, 2021). "Apart from meningiomas, there is no clear association between ARMC5 genetic alterations and sporadic nor familial other tumor type." (PMID 39910635, 2025). "Unlike meningiomas, the role of ARMC5 variants in these lesions, which do not exhibit second hits or loss of heterozygosity, remains unclear." (PMID 40895499, 2025). "Meningioma has been reported in patients with ARMC5 mutation; it was not seen in our patient." (PMID 39887684, 2025). "The finding also illustrates why the knockout of ARMC5 inhibits T cell proliferation and differentiation into TH1 and TH17 cells and increases T cell apoptosis and why ARMC5 mutations may cause meningioma." (PMID 34912852, 2021).
hypercortisolism (10 papers, 2018 to 2026). "In most cases, PBMAH caused by ARMC5 mutation results in hypercortisolism; however, in rare situations, hyperaldosteronism occurs." (PMID 39518893, 2024). "Of note, both the positive and the negative responders to hCRH were well-comparable regarding gender, age, degree of initial hypercortisolism, and ARMC5 mutational status." (PMID 37796369, 2024). "Patients present more frequently with hypertension, most likely because of the more severe hypercortisolism, but ARMC5 variants have also been associated in African Americans with low renin hypertension, higher fasting glucose, and HbA1c." (PMID 34680514, 2021). "Only one patient had AI nodules with subclinical hypercortisolism and autonomous cortisol secretion presenting the germline pathogenic allelic variant c.1084C > T p.Arg362Trp in exon 3 of ARMC5 (35*)." (PMID 32117062, 2020). "Over the past 9 years, we have observed that the majority of Brazilian family members with PMAH present with mild symptoms of hypercortisolism, despite the presence of bilateral adrenal nodules and germline ARMC5 mutations." (PMID 32117062, 2020). "Several ARMC5-mutated family members exhibited mild hypercortisolism or normal cortisol secretion; therefore, ARMC5 gene screening can help identify those insidious patients." (PMID 29370219, 2018). "ARMC5 pathogenic germline mutations were identified in 5 sporadic PBMAH patients among whom one patient displayed both hypercortisolism and primary aldosteronism." (PMID 29370219, 2018). "Phenotype–genotype relations studies showed that patients with the ARMC5-damaging mutation exhibited a more severe hypercortisolism and larger adrenals compared to patients with the wild-type." (PMID 29343284, 2018). "Both study groups (BMAHremission, BMAHactive) were well-comparable regarding gender, age at initial diagnosis, degree of hypercortisolism at initial diagnosis (considering UFC and cortisol after 1 mg-DST), ARMC5 mutational status, and side of U-Adx." (PMID 37796369, 2024). "The authors did not identify any pathogenic allelic variants of ARMC5, even in cases with subclinical hypercortisolism, by DST (51% of cases)." (PMID 32117062, 2020). "PBMAH family members with ARMC5 germline mutations could display mild hypercortisolism or normal cortisol secretion without an obvious cushingoid appearance." (PMID 29370219, 2018). "Moreover, these ARMC5-mutated family members without obvious clinical manifestations should be followed up throughout their lifetime because the phenotype may progress to overt hypercortisolism and the adrenals may grow larger in the future." (PMID 29370219, 2018).